NGF (nerve growth factor)
Diseases named in the same sentence as NGF in open-access papers (continued):
Sharing a sentence is not in itself a finding about the gene and the disease.
endometriosis (continued). "Together with upregulation of inflammatory mediators such as IL-6, COX-2, and NGF, these findings support a model of widespread immune activation and systemic mast-cell priming, indicating that histamine signaling in endometriosis is both locally active and systemically amplified." (PMID 41516088, 2025). "Immunolocalization for nerve bundle density around endometriosis using protein gene product 9.5 (PGP9.5), as well as NGF and IL-1β histoscores in endometriosis epithelium/stroma, was performed to evaluate differences in scores between lesions and anatomic subtypes per patient." (PMID 38785989, 2024). "These cytokines promote ESC proliferation and induce the upregulation of nerve growth factor, which may represent the primary mechanism by which DNG relieves endometriosis-associated pain." (PMID 36428561, 2022). "Other factors that may be potential markers in the diagnosis of endometriosis are interleukin 8, vascular endothelial growth factor, platelet-derived growth factor, and nerve growth factor." (PMID 34681755, 2021). "Another consequence of estrogen in endometriosis is its ability to affect peripheral nerve fibres directly or indirectly through the upregulation of various growth factors, including nerve growth factors (NGF), contributing to nociceptive pain." (PMID 34073257, 2021). "Based on the present study, it is speculated that patients with increased local secretion of NGF, such as adenomyosis or endometriosis, anti-NGF therapy may improve their pregnancy outcome slightly." (PMID 32676925, 2021). "NGF is a neurotrophic factor but is also elevated in lesions of endometriosis." (PMID 32145751, 2020). "NGF also plays a role in the change of nerve fibers in endometriosis." (PMID 32145751, 2020). "NGF is highly expressed in the peritoneal fluid, ovary, and uterus of endometriosis patients." (PMID 33339236, 2020). "First, several factors involved in nerve growth and found upregulated in women with endometriosis have been found to be regulated by E2, including nerve growth factor (NGF), vascular endothelial growth factor (VEGF), and brain-derived neurotrophic factor (BDNF)." (PMID 31387263, 2019). "Thus, our results support the concept that NGF is involved in neuronal development and likely pain generation from peritoneum in endometriosis." (PMID 27519317, 2016). "Mast cells appear to play an important role in the development of endometriosis and have been found in the implanted tissue, proximal to nerves, and are thus well placed to release numerous mediators, such as NGF, and thereby contribute to endometriotic pelvic pain." (PMID 27790149, 2016). "Nerve growth factor (NGF) levels are higher in the follicular fluid of women with endometriosis." (PMID 22203846, 2011). "Histological analysis of human deep innervating endometriosis (DIE) tissue showed strong expression of NGF in endometriotic glands and stroma of DIE which may play a role in the pathways involved in the intense pelvic pain that patients experience." (PMID 22203846, 2011). "Several studies have suggested that abnormal expression of NGF in adenomyosis and endometriosis might be involved in the pathomechanism of these diseases." (PMID 21385399, 2011). "One study found that there were no nerve cells in endometriotic lesions; however, BDNF and NGF could promote the generation of nerve tissue in endometriotic lesions, and the expression levels of BDNF and NGF were correlated with the degree of pain in endometriosis patients." (PMID 35300713, 2022). "Similarly, we were able to replicate a recent finding in EUR and Chinese samples for dysmenorrhea pain severity in the NGF gene locus, and we further identified a novel dysmenorrhea association in the IL1 gene locus that is in LD with known endometriosis associated variants." (PMID 29855537, 2018).
endometriosis (continued). "Higher levels of inflammatory mediators such as tumor necrosis factor α (TNFα), interleukins, prostaglandin E2 (PGE2), nerve growth factor (NGF) and chemokine RANTES/CCL5 were found in lesions and perioneal fluid of endometriosis patients." (PMID 40948761, 2025). "The inflammatory mediators in endometriosis include prostaglandins, interleukins (IL), vascular endothelial growth factor (VEGF), tumor necrosis factor (TNF-α), and nerve growth factor (NGF)." (PMID 36983810, 2023). "The results showed significant decreases in the serum and PF‐BDNF, serum‐NGF, and CGRP in the endometriosis group compared to other groups in phase one." (PMID 34806344, 2021). "The concentrations of BDNF, NGF, and CGRP in DRG of the endometriosis group were significantly higher than these factors in the Control, Sham‐1, and RJ groups (p < 0.05)." (PMID 34806344, 2021). "Neuroangiogenesis is regulated by estrogen and immune cells, including macrophages, which are an important source of vascular endothelial growth factor (VEGF) and nerve growth factor (NGF), both of which are increased in endometriosis." (PMID 33132854, 2020). "In women with endometriosis, inflammatory mediators including interleukin (IL)-1β, IL-6, tumor necrosis factor (TNF)-α, prostaglandins (PGs) and nerve growth factor (NGF) have been demonstrated to be elevated in peritoneal fluid and/or endometriotic lesions." (PMID 28898282, 2017). "TGF-ß1 is known to affect the expression of growth factor (NGF) and neurotrophin-3 (NT-3) mRNA, and as ILK remains under TGF-ß1 control, the involvement of ILK in the mechanism of pelvic pain in women with endometriosis is therefore possible." (PMID 36768775, 2023). "Previous studies have also shown that women diagnosed with endometriosis had higher concentrations of IGF-1 and NGF in the peritoneal fluid than women without endometriosis." (PMID 36879305, 2023). "In contrast, another study compared pain groups of endometriosis based on dysmenorrhea and pelvic pain, and found no significant changes in NGF level in peritoneal fluid or when using this peritoneal fluid to induce neurite outgrowth from dorsal root ganglia." (PMID 38098984, 2023). "In endometriosis, the inflammatory mediators secreted include prostaglandins, vascular endothelial growth factor (VEGF), tumor necrosis factor (TNF-α), nerve growth factor (NGF), and interleukins (IL)." (PMID 33435569, 2021). "There is an abundance of inflammatory molecules, including glycodelin, ROS, TNFα, NGF and PGE2 in the peritoneal fluid of women with endometriosis, which may contribute to the induction of a more pro-nociceptive state." (PMID 33132854, 2020). "The main objective of this immunohistochemistry study was to assess for the presence and localization of the neurotrophins NGF and BDNF and their receptors, TrkA and, TrkB and p75, in endometriosis lesions and to compare these between PE and DIE by using quantitative methods." (PMID 27519317, 2016). "Neurotrophins [nerve growth factor (NGF), brain derived neurotrophic factor (BDNF), neurotrophin-4] and other growth factors [vascular endothelial growth factor (VEGF) and transforming growth factor beta (TGF-β)] are increased in the peritoneal fluid of women with endometriosis." (PMID 36303969, 2021). "We performed correlation analyses between NGF and BDNF immunostaining and nerve fiber density (PGP9.5 staining) for both gland and stroma, and for the subtypes of endometriosis (PE and non-bowel DIE)." (PMID 27519317, 2016). "The spatial relationship between the main neurotrophins (NGF and BDNF) and their receptors (TrkA, TrkB, p75) in histological sections from endometriosis tissue has not been extensively studied so far." (PMID 27519317, 2016).
glioma (45 papers, 2012 to 2025). A benign or malignant brain and spinal cord tumor that arises from glial cells (astrocytes, oligodendrocytes, ependymal cells). "NGF promotes the growth, proliferation, aggressiveness, and angiogenesis of glioma cells in an α9β1 integrin-dependent manner." (PMID 40783715, 2025). "Intriguingly, in benign and malignant gliocytes, pro-oncogenic signals contribute to the production of NGF, indicating potential positive feedback in accelerating glioma progression." (PMID 40783715, 2025). "The neuroprotective potential of the isolated compounds was assessed by measuring nerve growth factor (NGF) secretion in C6 glioma cells." (PMID 40243996, 2025). "Some of these terpenoids exhibited inhibitory effects on NO production, a significant stimulating effect on nerve growth factor (NGF) secretion in C6 glioma cells, and a neurotrophic effect." (PMID 37049509, 2023). "Hericerin, a related compound, has neurotrophic properties through the increased production of nerve growth factor in C6 glioma cells." (PMID 37627983, 2023). "NGF and the peptides showed a strong cytotoxic effect on U251 glioma cells in the MTT test (IC50 0.0214, 3.1, and 26.1 μM, respectively) compared to chemotherapy." (PMID 38002009, 2023). "NGF (200 ng/mL) also inhibited the migration of U87 glioma cells, but it stimulated the migration of SF767 glioma cells via the expression of the p75NTR receptor." (PMID 35956937, 2022). "We demonstrated that LL-37 (4 μM) and NGF (7.55 × 10−3 μM) inhibited the clonogenicity of glioma U251 cells during the first and second days." (PMID 35956937, 2022). "LL-37 (4 μM), TMZ (155 μM), and NGF (7.55 × 10−3 μM) inhibited 43.9%–60.3%, 73.5%–81.3%, 66.2% the clonogenicity of glioma U251 cells for 1–2 days, respectively." (PMID 35956937, 2022). "It was shown that LL-37, PG-1 and NGF also exhibited strong antitumor effects on C6 glioma cells when applied at less than 10−4 M. Synergistic effects for combinations of PG-1 with carboplatin and LL-37 with etoposide were shown." (PMID 35056889, 2022). "To establish the cytotoxic antitumor efficacy of NGF, PG-1, and LL-37 combinations with chemotherapeutic agents on C6 glioma cell culture, we compared their IC50 with the IC50 of chemotherapy using an MTT assay and trypan blue staining." (PMID 35056889, 2022). "Combinations of S. pyogenes strain #7 with NGF or LL-37 demonstrated a cytotoxic effect (56.7% and 57.3%, accordingly) on C6 glioma cells after 3 h of exposure." (PMID 35056889, 2022). "Although findings from an earlier report indicate that SorCS3 binds NGF and that NGF is an influencing factor of glioma cell progression, the functional implications of these interactions are poorly understood." (PMID 35393432, 2022). "Glycolysis, glycolytic capacity and glycolytic spare in glioma U251 cells haven`t been changed under the effect of NGF, LL-37, PG-1, and TMZ in regard to control level." (PMID 35956937, 2022). "LL-37 (4 μM), and NGF (7.55 × 10−3 μM) inhibited the migration of U251 glioma cells on the third and fourth days." (PMID 35956937, 2022). "We selected S. pyogenes 7 and S. pyogenes 21 strains as having the fastest cytotoxic effect on C6 glioma and studied their effect in combination with PG-1, LL-37, NGF and TMZ in real time when added at the stationary phase of cell line growth." (PMID 35056889, 2022). "The perspective of the antitumor effect of NGF and the combination of NGF with chemotherapy on glioma cell cultures has been studied insufficiently." (PMID 35056889, 2022). "In order to determine the cytotoxic antitumor efficacy of NGF, PG-1, and LL-37 on C6 glioma cells, their effect was compared by IC50 and by the efficacy of chemotherapy drugs according to the results of the MTT assay and trypan blue staining." (PMID 35056889, 2022). "The impact of NGF was decreased, and the proliferation activity of glioma cells was increased in 2 days, wherein we observed a high percentage of single cells (20%)." (PMID 35956937, 2022).
glioma (continued). "In order to develop new strategies for the tumor treatment, we studied the effects of NGF, PG-1, LL-37, their combinations with chemotherapy and live oncolytic bacteria on the C6 glioma cell culture." (PMID 35056889, 2022). "We investigated the migration of human glioma U251 cells under the effects of LL-37, NGF, PG-1, and TMZ over 1–6 days." (PMID 35956937, 2022). "Combinations of S. pyogenes 21 with NGF and S. pyogenes 21 with LL-37 have a pronounced cytostatic effect on C6 glioma cells, but less so than if administered separately." (PMID 35056889, 2022). "This indicates a lower cytotoxic efficiency of the combinations of PG-1 and NGF with selected chemotherapy drugs and LL-37 with temozolomide in the culture of C6 glioma cells." (PMID 35056889, 2022). "Based on these findings and taking into account the positive clinical outcome obtained with conjunctival NGF administration in terms of visual rescue in OG patients, the effect of exogenous NGF on low-grade glioma remains an open question." (PMID 34257579, 2021). "Previous studies from others and us have demonstrated the central regulator role of p75NTR in glioma migration and invasion, which transduces the glioma malignant signaling through nerve growth factor-p75NTR interaction and γ-secretase cleavage." (PMID 34357080, 2021). "In the present study, establishment, preliminary characterization and analysis of responsivity to exogenous NGF of a patient-derived cell line and its hTERT-transduced counterpart from a human pediatric low-grade glioma is reported." (PMID 34257579, 2021). "Endogenous NGF expression has been reported to increase with glioma aggressiveness, while exogenous NGF is involved in the regulation of glioma cell growth in vivo." (PMID 34257579, 2021). "Treatment with increasing concentrations of NGF produced distinctive responses in the different glioma cells analyzed, in terms of cell survival." (PMID 34257579, 2021). "LGG2 cells transduced with hTERT were able to grow in culture for a sufficiently long time to allow the analysis of additional biological features potentially involved in NGF-mediated glioma differentiation." (PMID 34257579, 2021). "Unfortunately, the slow growth rate of low-grade gliomas (LGG) has made it difficult to investigate NGF effects on these tumors in preclinical models." (PMID 34257579, 2021). "We found that KYJ (124.36 ± 1.95% at 10 μg/ml; 159.56 ± 7.14% at 25 μg/mL) significantly increased NGF production in C6 glioma cells, which are representative cells of astrocytes." (PMID 32403381, 2020). "The KYJ combination increased NGF concentration and neurite length in C6 glioma and N2a neuronal cells, respectively." (PMID 32403381, 2020). "In this study, Equol substantially increased the secretion of NGF in C6 glioma cells, suggesting a neuroprotective effect." (PMID 28264445, 2017). "N2a cells were treated with malathion and then the culture media was collected and used to culture C6 glioma cells for 24 h, at which point cell viability and soluble NGF secretion were measured." (PMID 28487766, 2017). "We showed that malathion caused a host of neurodegeneration-related events such as blockage of neurite outgrowth, reduced expression of the neuronal proteins VEGF and hFABP3 in N2a cells, and reduced secretion of NGF in C6 glioma cells." (PMID 28487766, 2017). "Earlier studies also indicated that NGF activity and content were found to be increased by estradiol in a glioma cell line culture." (PMID 24405743, 2014). "The expression level of NGF in glioma is nearly threefold higher than that in the normal brain." (PMID 40783715, 2025). "Interestingly, the authors assessed the neuroprotective activities of the isolated compounds by measuring their ability to induce nerve growth factor (NGF) secretion in C6 glioma cells." (PMID 39063085, 2024). "Interestingly, corallocin A, isolated from H. erinaceus, exhibited similar activity in another study, inducing NGF protein expression in C6 glioma cells." (PMID 38892137, 2024).
glioma (continued). "The aim of current study was to investigate the effects of nerve growth factor (NGF), human cathelicidin (LL-37), protegrin-1 (PG-1), and temozolomide on bioenergetic function of mitochondria, clonogenicity, and migration of human U251 glioma cells." (PMID 35956937, 2022). "However, after NGF treatment, the effect of SorCS3 was amplified in two glioma cell lines (U87 and U251)." (PMID 35393432, 2022). "The study of the mechanisms of these effects may contribute in the future to the use of NGF and LL-37 as therapeutic agents for gliomas." (PMID 35956937, 2022). "Notably, all combinations of chemotherapy drugs with LL-37 and NGF showed very strong antagonism (CI > 10) in the culture of C6 glioma." (PMID 35056889, 2022). "Similarly, NGF (100 μg/mL, 7.55 × 10−3 μM) also inhibited 66.2% (p = 0.0152) of the clonogenic capability of human glioma U251 cells over 1 day." (PMID 35956937, 2022). "Thus, the resilient amount of NGF regulated by HRE can prevent the possible glioma provoked by unlimited NGF release." (PMID 34675188, 2021). "Previously, we reported that diterpenes isolated from A. holophylla have anti-inflammatory effects in LPS-activated murine microglial cells (via reduced NO production) and neuroprotective properties in C6 glioma cells (via increased nerve growth factor secretion)." (PMID 33478055, 2021). "Furthermore, the expression of the nerve growth factor (NGF) in CSF was found to be more elevated as the malignancy of the glioma increased." (PMID 31284524, 2019). "Moreover, the reduced expression patterns of stemness-associated genes (MYC and SOX2) and the reactivation of neuronal differentiation-associated genes (BDNF, NGF, and NTF3) were clearly observed in the asTUG1/uPIC-treated glioma tissues." (PMID 31019193, 2019). "In addition, we will examine neurite outgrowth in malathion-treated N2a cells and nerve growth factor (NGF) secretion from C6 glioma cells treated with N2a-conditioned media in order to establish an in vitro AD model." (PMID 28487766, 2017). "So, we investigated the level of soluble NGF secreted by C6 glioma cells." (PMID 28487766, 2017). "Likewise, recent studies indicate that topical ocular NGF administration reduces glioma in vivo and the progression of pediatric optic glioma." (PMID 27439311, 2016). "The in vitro release study showed that TP-NGFP-TP membrane could efficiently liberate TMZ to inhibit the growth of C6 glioma cells, and sufficient NGF to induce the differentiation of PC12 neuron cells over four weeks." (PMID 27548322, 2016). "Furthermore, knowing that CK2 controls NFs by the direct activation of cascade transduction signaling and BDNF or NGF released by glioma cells promoting tumor growth depending on the presence of microglia, we found a link that exists between neurotrophins-induced signals and regulation of CK2." (PMID 39682125, 2024). "The neurotrophin nerve growth factor (NGF) modulates the growth of human gliomas and is able to induce cell differentiation through the engagement of tropomyosin receptor kinase A (TrkA) receptor, although the role played in controlling glioma survival has proved controversial." (PMID 34257579, 2021). "Moreover, malathion-exposed N2a cells showed a marked reduction in the levels of the neuronal marker proteins vascular endothelial growth factor and heart fatty acid binding protein 3, along with diminished neuritogenesis in N2a cells and nerve growth factor secretion in C6 glioma cells." (PMID 28487766, 2017). "A perspective on future development for translational research on NGF is also discussed, in view of recent proposals for innovative delivery strategies and/or for additional pathologies to be treated, such as ocular and skin diseases, gliomas, traumatic brain injuries, vascular and immune diseases." (PMID 23190582, 2012). "We also tested the transcript level of the nerve growth factor (NGF) that, through the binding to receptor p75NTR, is involved in glioma proliferation." (PMID 36142158, 2022).